HIF1A (hypoxia inducible factor 1 subunit alpha)
Diseases named in the same sentence as HIF1A in open-access papers (continued):
Sharing a sentence is not in itself a finding about the gene and the disease.
colorectal cancer (continued). "circEXOC6B associates with RRAGB to antagonize HIF1A-RRAGB-mTORC1 positive feedback loop for enhancing 5-fluorouracil-induced apoptosis and repressing colorectal cancer growth." (PMID 40651979, 2025). "Glutaminase 1 (GLS1), the rate-limiting enzyme in glutaminolysis, is transcriptionally regulated by c-Myc, HIF1α, and the Wnt/β-catenin signaling pathway, which are critical drivers of colorectal cancer." (PMID 41488637, 2025). "In summary, our study demonstrates that Curcumol inhibits colorectal cancer (CRC) progression by activating the VHL/HIF-1α pathway, suppressing glycolysis and lactate production, and improving tumor microenvironment." (PMID 41008845, 2025). "This article precisely focuses on the context of colorectal cancer, delving deep into the interactions between these ncRNAs and HIF-1α." (PMID 40305214, 2025). "One study demonstrated that the transcription factor HIF-1α enhances the transcription of LINC00511 in colorectal cancer cells." (PMID 40861273, 2025). "Hypoxia-inducible factor-1α (HIF-1α), a master regulator of cellular adaptation to hypoxia, drives colorectal cancer (CRC) progression by fueling angiogenesis, metastasis, and therapy resistance." (PMID 40305214, 2025). "Among the upregulated target genes, we highlighted six that are closely linked to colorectal cancer: LGALS9, GLUT1, IGFBP3, CDK4, DUSP1, and HIF1A." (PMID 41411347, 2025). "Blocking the interaction of IL-6 and IL-6R in colitis-associated colorectal cancer (CAC) by anti-IL-6 receptor antibodies reduced the size and number of tumors in mice, and the effect was mediated by the downregulation of HIF-1α." (PMID 40430040, 2025). "This study is the first to reveal that Curcumol suppresses the progression of colorectal cancer (CRC) by activating the VHL/HIF-1α signaling pathway, thereby significantly inhibiting hypoxia-driven glycolysis." (PMID 41008845, 2025). "XIST acts as a ceRNA for miR-93-5p, promoting colorectal cancer metastasis partially through HIF-1A/AXL signaling." (PMID 40861273, 2025). "In this study, we explored the prognostic impacts of HIF-1α, LOX and ITGA5 expression in the tumor microenvironment and their relationship with KRAS/NRAS/BRAF mutation status in colorectal cancers." (PMID 39857068, 2025). "In the context of colorectal carcinomas, HIF-1α is notorious for supporting angiogenesis, metabolic reprogramming, and resistance to therapy." (PMID 41515404, 2025). "The HIF pathway, including HIF‐1α, EPAS1, HIF‐3α and ARNT, is associated with disease progression and adverse clinical outcomes in colorectal cancer." (PMID 37994607, 2024). "For example, ROD1 can bind to IRES region in HIF-1α mRNA and participates in colorectal cancer growth and invasion through activating HIF-1α translation." (PMID 38573528, 2024). "Through meticulous bioinformatics analysis, Liu and colleagues identified that the upregulation of HTBS2 expression in colorectal cancer cells facilitates the nuclear translocation of HIF-1α." (PMID 39456135, 2024). "In colorectal cancer, HIF-1α/miR-338-5p/IL-6 axis activation in response to hypoxic conditions is also reportedly conducive to tumor growth." (PMID 38440120, 2024). "In this study, the synergistic effects of gene-targeting HIF-1α siRNA combined with Toll-Like Receptor 7 agonist on TME remodeling were investigated in a mouse model of colorectal cancer (CRC)." (PMID 39614894, 2024). "For instance, treatment with brusatol, an inhibitor of NRF2 protein synthesis, prevents hypoxia-induced HIF-1α accumulation and reduces glucose consumption in colorectal cancer cells." (PMID 38424190, 2024). "The hypoxic tumor microenvironment of colorectal cancer induces HIF1α expression, thereby increasing FSTL3 levels." (PMID 39223632, 2024). "Hypoxia can inhibit hypoxia-induced ROS/ER stress signaling and promote proliferation and clone formation in colorectal cancer cells by inducing TXNDC5 overexpression through the upregulation of HIF-1α." (PMID 38629066, 2024).
colorectal cancer (continued). "In colorectal cancer, cancer-associated fibroblasts (CAFs)-secreted TGFB2 and hypoxia-inducible factor (HIF-1α) interact to activate the expression of hedgehog transcription factor GLI2 in cancer stem cells, resulting in intrinsic resistance to chemotherapy." (PMID 38914663, 2024). "In colorectal cancer cells, the expression of HIF1α increases in the hypoxic tumor microenvironment." (PMID 39223632, 2024). "As the oncogenic effector, HIF1α consequently facilitates colorectal cancer proliferation and metastasis." (PMID 39550559, 2024). "Superoxide dismutase 3 has been shown to be related to the regulation of HIF-1α, which participates in the process of several malignancies, such as breast, lung, pancreatic, and colorectal carcinomas." (PMID 39234408, 2024). "In an in vitro experiment, we demonstrated that hypoxia-inducible factor 1α (HIF-1α), which was induced in this hypoxic environment, prevented cell death and promoted the therapeutic resistance of colorectal cancer cells." (PMID 37198556, 2023). "14-3-3σ reportedly recruited S448-phosphorylation of NEDD4L to mediate ubiquitination and downregulation of hypoxia-inducible factor-1a (HIF-1a), thereby inhibiting colorectal cancer angiogenesis and enhancing sensitivity to bevacizumab." (PMID 38027016, 2023). "DKC1 has been shown to regulate the NF-κB/MMP-2 pathway in ccRCC, and improve HIF-1α transcription levels by binding its promoter region in colorectal cancer." (PMID 38082360, 2023). "Overexpression of circ-Erbin in colorectal cancer cells significantly increased the angiogenesis rate by upregulating HIF-1α expression." (PMID 37394582, 2023). "Accordingly, undifferentiated cells expressing HIF-1α and enriched in mesenchymal phenotypes have been observed at the invasive edge of colorectal cancer." (PMID 37540301, 2023). "CIRC-Erbin sponges miR-125a-5p and miR-138-5p, targeting eukaryotic translation initiation factor 4E-binding protein 1 (4EBP-1) and accelerating HIF-1α capsid protein translation in colorectal cancer cells." (PMID 37394582, 2023). "An isoquinoline alkaloid, berberine, inhibited the overactive glucose metabolism of HCT116 and KM12C colorectal cancer cells by suppressing mTOR-dependent HIF-1α protein synthesis." (PMID 35890106, 2022). "In this study, the DNA-demethylating agent zebularine induced HIF1α protein degradation via hydroxylation, reduced tumor angiogenesis and potentiated the anticancer effect of oxaliplatin in an induced colorectal cancer model." (PMID 36551845, 2022). "Another study demonstrated that targeting HIF1α was a promising approach to face chemo-resistance in colorectal cancer." (PMID 36551845, 2022). "In conclusion, these findings showed that LINC00525 was essential for hypoxia-enhanced glycolysis; its mechanism was related to activating HIF-1α through miR-338-3p/UBE2Q1/β-catenin axis in colorectal cancer cells." (PMID 35156520, 2022). "One such example is lincRNA-p21, which is transcriptionally induced by HIF-1α under hypoxia, can in turn interrupt the HIF-1α-VHL interaction, thereafter stabilizing HIF-1α and upregulating genes involved in glycolysis in colorectal cancer cells." (PMID 35842651, 2022). "More recently, a study also reported that Grim-19 repressed hypoxia-induced invasion and epithelial-mesenchymal transition by repressing autophagy through inactivation of the STAT3/HIF-1α signaling axis in colorectal cancer." (PMID 36387896, 2022). "The goal of this study was to demonstrate that LINC00525 activated HIF-1α through miR-338-3p/UBE2Q1/β-catenin axis to regulate the Warburg effect in colorectal cancer." (PMID 35156520, 2022). "The previous study has found that UBE2Q1 was highly expressed in colorectal cancer, and increased the levels of β-catenin protein by stabilizing β-catenin in cancer cells, and β-catenin interacts with HIF-1α under hypoxic condition." (PMID 35156520, 2022).
colorectal cancer (continued). "A previous study showed that OL inhibits the proliferation of colorectal cancer cells through downregulation of HIF-1α." (PMID 36050634, 2022). "Tan IIA also repressed the expression of pro-angiogenic factors (VEGF and bFGF) and HIF-1α in colorectal cancer (CRC) HCT-116 cells and adversely regulated proliferation and tube formation of HUVECs." (PMID 35784750, 2022). "Studies have found that baicalein can target TLR4/HIF-1α/VEGF signaling pathway in the treatment of colorectal cancer." (PMID 36415861, 2022). "Tan IIA suppressed β-catenin/TCF3/LEF1/VEGF by TGF-β1 at normoxia while by HIF-1α at hypoxia to astrict angiogenesis in colorectal cancer." (PMID 35784750, 2022). "We compared the efficiency of CCRT in hyperglycemic rectal cancer and euglycemic colorectal cancer and analyzed the expression of HIF-1α in tumors to define the relationship between them." (PMID 36011045, 2022). "Larsen reported that the expression of HIF1A was significantly higher in BV-resistant colorectal cancer cell xenografts than BV-sensitive xenografts, indicating that upregulation of HIF1A was a potential resistant mechanism for BV." (PMID 34477158, 2021). "For example, epidermal growth factor (EGF) increases the activation of STAT3 through its phosphorylation, thus inducing HIF-1α upregulation and promoting the proliferation and metastasis of colorectal cancer cells." (PMID 34365889, 2021). "Britannin interrupts mTOR signaling and inhibits MYC proto-oncogene (MYC), as well as HIF-1α expression in TNF-treated colorectal cancer cells." (PMID 34575983, 2021). "In our present studies, dual targeting of CDK1 or CDK4/6 and HSP90 robustly reduced the level of HIF1α and synergistically inhibited cell viability in colorectal cancer lines." (PMID 34686682, 2021). "Further exploration of piceatannol revealed that NF-κB and HIF-1α levels are downregulated in colorectal cancer cells exposed to piceatannol-loaded nanoparticles (PNs)." (PMID 34575983, 2021). "To improve our understanding of HIF-1α stabilization by CDKs and gain novel insights into the mechanisms of HIF-1α regulation in cancer, we performed a proteomic analysis on immunoprecipitated HIF-1α from colorectal cancer cells treated in hypoxia." (PMID 34611473, 2021). "In colorectal cancer tumor masses, cells become hypoxic because of clumping, and production of the hypoxia inducible factor alpha (HIF-1α) is induced, which directly activates KDM4B transcription and translation." (PMID 35186950, 2021). "For example, HIF-1α is upregulated in colorectal cancer cell lines and contributes to angiogenesis by modulating the expression of EMT-related molecules claudin-4, E-cadherin and Vimentin." (PMID 34036383, 2021). "In colorectal cancer cells, panaxadiol suppresses HIF-1α expression via the PI3K/AKT pathway under hypoxia." (PMID 34575983, 2021). "Proteasomal degradation of HIF-1α is prompted by decursin in lung and colorectal cancer cells under hypoxia." (PMID 34575983, 2021). "Worenine is a major active component of Coptidis Rhizoma, which inhibits colorectal cancer cell growth by negatively regulating HIF-1α." (PMID 34539797, 2021). "Away from its role on telomeres, DKC1 has been shown to bind HIF1α promoter and increases the expression of HIF1α in colorectal cancer (CRC)." (PMID 33599797, 2021). "Not only do PNs inhibit colony formation and invasion activities of cancer cells in vitro, but PNs suppress the growth of colorectal cancer in vivo, suggesting that the NF-κB/HIF-1α axis partly mediates the anti-cancer effects of piceatannol." (PMID 34575983, 2021). "Reduction of HIF-1α proteins took place without an alteration of mRNA levels and protein stability in CoCl2-treated colorectal cancer cells, suggesting the ability of kamebakaurin to inhibit translation of HIF-1α mRNA." (PMID 34575983, 2021). "Another study found miR-206 suppressed the Met/ERK/Elk-1/HIF-1α/VEGF-A pathway in CCL19-mediated colorectal cancer cells." (PMID 34697590, 2021).
colorectal cancer (continued). "Verbascoside adversely affects HIF-1α expression under normoxic conditions in colorectal cancer and downregulates EMT-related factors such as zinc finger E-box-binding homeobox 1 (ZEB1)." (PMID 34575983, 2021). "miR-21 proved to be a regulator of angiogenesis in prostate, lung, and colorectal cancers, modulating hypoxia inducible factor-1α (HIF-1α) and vascular endothelial growth factor (VEGF)." (PMID 34440094, 2021). "It is reported that brusatol treatment downregulated mitochondrial ROS levels, leading to diminished HIF-1α protein levels and cell death in colorectal cancer under hypoxia." (PMID 33542787, 2021). "Immunohistochemical analysis evidenced the expression of both Sema4D and HIF-1α in about 60% of colorectal carcinoma tissue and in about 10% of normal mucosa." (PMID 33858502, 2021). "It is noteworthy that HIF-1α is previously reported to activate STAT3 by repressing miR-34a in colorectal cancer." (PMID 33681184, 2020). "Specifically, immunohistochemistry analysis of HIF-1α and VEGF in colorectal polyps and colorectal cancers showed that both HIF-1α and VEGF were expressed in most (78–93%) of serrated precursors." (PMID 32183342, 2020). "Here, we report that XIST promotes colorectal cancer tumorigenesis by regulating miR‐93‐5p/HIF‐1A/AXL signaling pathway." (PMID 32061057, 2020). "This would make NF-κβ and HIF-1α proteins potential targets for effective treatment of colorectal cancer." (PMID 31906321, 2020). "Colorectal cancer patients with elevated NQO1 expression have been shown to correlate with high-level of HIF-1α expression and poor prognosis." (PMID 31909204, 2020). "In contrast, lncRNA HITT inhibits angiogenesis in colorectal cancer cells by inducing the cleavage of YB-1 from the 5′-UTR region of HIF-1α protein, resulting in HIF-1α protein degradation." (PMID 32993787, 2020). "In colorectal cancer, hypoxic microenvironment-induced HIF-1α expression upregulates EMT-related molecules such as claudin-4, vimentin, and E-cadherin, promoting EMT-induced vasculogenic mimicry." (PMID 32993787, 2020). "The role of hypoxia-inducible factor-1α (HIF-1α) in primary colorectal cancer (CRC) and colorectal liver metastasis (CRLM) has remained unclear." (PMID 32895059, 2020). "IFN-α can increase HIF-1a expression and promote vasculogenic mimicry in the kidney, breast, ovarian, and colorectal cancer cells by activating PI3K/AKT/mTOR signaling." (PMID 32993787, 2020). "Here we studied the role of HIF-1α-mediated response towards hypoxia in an orthotopic colorectal cancer model in immunocompetent mice." (PMID 33142239, 2020). "HIF1A-AS1, located in the antisense strand of human HIF-1α gene, was recognized as an oncogene in non-small cell lung cancer and colorectal cancer." (PMID 32473641, 2020). "In the present research, in order to determine if XIST modulates the activities of colorectal cancer by HIF‐1A/AXL signaling, the expression of AXL after loss‐ and gain‐of‐function of XIST was detected in colorectal cancer cells." (PMID 32061057, 2020). "It is well documented that pro-inflammatory cytokines induce aberrant activation of NF-κβ and HIF-1α in ulcerative colitis and colorectal cancer patients." (PMID 31906321, 2020). "XIST is a ceRNA for miR‐93‐5p to promote the progression of colorectal cancer partly through HIF‐1A/AXL signaling." (PMID 32061057, 2020).
colorectal cancer (continued). "The extract of Salvia miltiorrhiza can effectively inhibit the proliferation, tubule formation and metastasis of human colorectal cancer cells by lowering HIF-1α levels and inhibiting the secretion of VEGF and bFGF." (PMID 32372960, 2020). "PDK1, a downstream target of hypoxia inducible factor 1 alpha (HIF1α), is upregulated in a number of cancers including ovarian cancer (OCa), gastric cancer (GCa), colorectal cancer (CRCa), PCa, and acute myeloid leukemia (AML)." (PMID 33384955, 2020). "The anti-angiogenic effect of cinobufagin by suppressing the mammalian target of rapamycin (mTOR) and hypoxia-inducible factor-1α (HIF1α) signaling pathways has also been observed in colorectal cancer." (PMID 32933177, 2020). "We found that HIF-1α protein does increase in HCT116 colorectal cancer cells exposed to OSA-like oxygen changes, and it alters gene and protein expression in pathways regulating glycolysis, hypoxia and extracellular matrix remodeling." (PMID 30669593, 2019). "In our previous studies, we focused on the effects of Hif1-α on the intestinal epithelial barrier and colorectal cancer." (PMID 31040849, 2019). "The hypoxia inducible factor 1 alpha (HIF-1α) induces EMT through direct regulation of ZEB1 as shown in colorectal cancer." (PMID 31121840, 2019). "HIF-1α/TGF-β2/GLI2 expression promotes stemness and chemoresistance in colorectal cancers and is associated with patient relapse following chemotherapy." (PMID 31244888, 2019). "Several previous findings indicate inflammation results in overstimulation of transcription protein such as p65 and HIF-1α in ulcerative colitis and colorectal cancer which results in damage of epithelial layer of colon." (PMID 30430451, 2019). "The hypoxia-mediated induction of NEDD9 expression in colorectal carcinoma cells significantly enhances HIF-1α transcriptional activity by modulating the interaction between HIF-1α and its transcriptional cofactor p300." (PMID 31462898, 2019). "Here, we further examined potential effects of IFN-α on HIF-1α expression in a panel of renal, breast, ovary and colorectal cancer cell lines." (PMID 29587825, 2018). "In colorectal cancer cell, β-catenin is translocated to the nucleus and interacts with HIF1α instead of TCF to adjust metabolic patterns during periods of hypoxia." (PMID 30547809, 2018). "In summary, we report a novel HIF-1 inhibitor, IDF-11774, which suppressed HIF-1α accumulation in colorectal cancer cells in vitro and in vivo." (PMID 28569777, 2017). "Taken together, these results are consistent with regulation of cell proliferation and glycolysis in colorectal cancer cells by a cascade controlled by the miR-1/Smad3/HIF-1α axis." (PMID 28471448, 2017). "In this study, IDF-11774 inhibited the accumulation of HIF-1α in vitro and in vivo in colorectal carcinoma HCT116 cells under hypoxic conditions." (PMID 28569777, 2017). "It has been previously demonstrated that Hsp90 promotes EMT in colorectal cancer via activation of HIF-1α, which results in a subsequent downregulation of Hsp90, leading to inhibition of EMT, motility, and invasiveness." (PMID 27248828, 2016). "We further performed the glucose uptake and lactate production, and colony formation assays to demonstrate the anti-RPS7 effect of HIF-1α on the growth of colorectal cancer cells." (PMID 26735579, 2016). "This is in line with in vitro studies where overexpressed HIF-1α in colorectal cancer cells resulted in enhanced GPx1 expression through TGF-βRI/Smad2/ERK1/2/HIF-1α signalling cascade, suggesting transcriptional regulation of GPx1 by HIF-1α." (PMID 27656047, 2016). "In colorectal cancer, hypoxia stabilizes the transcription factor HIF-1α, leading to the expression of genes that are involved in tumor vascularization, metastasis/migration, cell survival and chemo-resistance." (PMID 27144516, 2016).